KCNQ4 (potassium voltage-gated channel subfamily Q member 4)
Diseases named in the same sentence as KCNQ4 in open-access papers (continued):
Sharing a sentence is not in itself a finding about the gene and the disease.
deafness (21 papers, 2011 to 2024). An inherited or acquired condition characterized by the complete loss of the ability to hear from one or both ears. "Individuals III:3 and IV:3 inherited a heterozygous novel missense variant, c.1672G>A, p.(Val558Met), of KCNQ4, a gene known to cause dominant deafness in humans." (PMID 34946889, 2021). "The del(GJB6-D13S1830), SERPINB6, TMIE, COCH, ESPN, ACTG1, GJB3, and KCNQ4 mutations were infrequently associated with deafness in the Moravian-Silesian population." (PMID 30344259, 2018). "Another mutation in a gene of the same family, KCNQ4, was recently associated to deafness and hearing loss." (PMID 28449705, 2017). "The inhibition of KCNQ4 activity in the mammalian cochlea or knockout mouse causes sensory cell degeneration followed by deafness." (PMID 24555524, 2014). "The KCNQ4 p.W276S variant led to the onset of deafness in mice before 4 weeks." (PMID 36982769, 2023). "It has been reported that human KCNQ4 mutation can cause DFNA2 non-syndromic deafness." (PMID 34479475, 2021). "Drug repurposing and optimization for applicable specific KCNQ4 mutation might also be an option for clinical application of KCNQ4 activators in deafness treatment with advantages of reducing the cost and shortening the time when compared to de novo drug discovery." (PMID 33801540, 2021). "Mutations in nine deafness genes (COCH, KCNQ4, MYO7A, TECTA, CRYM, POU3F4, EYA1, mitochondrial tRNA(Lys) m.8296A>G, mitochondrial tRNA(Ser) m.7445A>G) were not identified in any patients." (PMID 22384008, 2012). "In three (III:3, IV:2, and IV:3) of the remaining four affected individuals, although we found rare and predicted damaging variants of known deafness genes (MPDZ, KCNQ4), however, these variants require further experimental studies to validate their pathogenic impact on the encoded proteins." (PMID 34946889, 2021). "This study presents a HL family GCUFAHL38, in which five different deafness genes (GJB2, SLC26A4, CDH23, MPDZ, KCNQ4) rare variants were co-segregating in different configurations, and thus further highlights the genetic complexity of hearing disorders in highly inbred families." (PMID 34946889, 2021). "Hotspot mutations in the deafness-associated genes are not uncommon, and have been reported for KCNQ4, ACTG1, WFS1, and TECTA." (PMID 32486382, 2020).
autosomal dominant non-syndromic deafness (8 papers, 2013 to 2024). "KCNQ4 is frequently mutated in autosomal dominant non-syndromic hearing loss (NSHL), a typically late-onset, initially high-frequency loss that progresses over time (DFNA2)." (PMID 31434872, 2019). "Many cases of autosomal dominant non-syndromic hearing loss (ADNSHL) arise from defects in KCNQ4, a protein that maintains the cellular ionic conditions needed for normal inner ear function." (PMID 31434872, 2019). "Moreover, mutations in KCNQ4, which encodes Kv7.4, are frequently associated with autosomal dominant nonsyndromic hearing loss." (PMID 39769024, 2024). "Autosomal dominant non-syndromic hearing loss (ADNSHL) is highly heterogeneous, among them, KCNQ4 is one of the most frequent disease-causing genes." (PMID 25116015, 2014). "Mutations in the KCNQ4 gene lead to DFNA2, a subtype of autosomal dominant non-syndromic deafness that is characterized by progressive sensorineural hearing loss across all frequencies." (PMID 23750663, 2013). "Loss-of-function variant in the gene encoding the KCNQ4 potassium channel causes autosomal dominant nonsyndromic hearing loss (DFNA2), and no effective pharmacotherapeutics have been developed to reverse channel activity impairment." (PMID 34316018, 2021).
age-related hearing loss (7 papers, 2011 to 2025). "This approach holds promise for preventing and treating age-related hearing loss caused by KCNQ4 variants." (PMID 40178561, 2025). "Furthermore, several single nucleotide polymorphisms in KCNQ4 are also reported to contribute towards age-related hearing loss, which is a complex disease rising from an alliance between genetic and environmental facets." (PMID 34946889, 2021). "In concordance with this hypothesis, a recent association study in two different human populations has linked KCNQ4 to age-related hearing loss, which may be attributable to the elevated expression of a causative KCNQ4 splice variant during ageing." (PMID 23750663, 2013). "As a result of this pivotal role, all missense and deletion mutations associated with KCNQ4 have been linked to a subtype of autosomal dominant non-syndromic sensorineural progressive hearing loss whose phenotype, like presbycusis, is characterized by reduced coding of higher frequencies." (PMID 34200434, 2021).
epilepsy (5 papers, 2014 to 2023). A brain disorder characterized by episodes of abnormally increased neuronal discharge resulting in transient episodes of sensory or motor neurological dysfunction, or psychic dysfunction. "KCNQ1 and KCNQ4 are expressed in multiple tissues (KCNQ4 in the auditory system and vasculature, KCNQ1 in the cardiovascular system and multiple epithelia) and their activation might cause unwanted off-target effects if one were instead intending to target KCNQ2 in epilepsy, for example." (PMID 31701029, 2019).
Hypertension (5 papers, 2016 to 2021). The presence of chronic increased pressure in the systemic arterial system. "Our data define a role for aberrant miR153 underlying this hypertensive state through targeting of KCNQ4 in an animal model of hypertension." (PMID 27389411, 2016). "miR153 is tumor suppressive, and miR153 targeting of KCNQ4 contributes to vascular dysfunction in hypertension." (PMID 31057422, 2019). "It should be emphasized that miR153-induced KCNQ4 down-regulation is only a contributory component in the multifactorial disease of hypertension." (PMID 27389411, 2016). "This study is the first to define a role for aberrant miR153 contributing to the hypertensive state through targeting of KCNQ4 in an animal model of hypertension, raising the possibility of the use of miR153-related therapies in vascular disease." (PMID 27389411, 2016). "Hence, the miR153 expression profile correlates closely with the Kv7.4/KCNQ4 expression profiles for the four arteries in hypertension." (PMID 27389411, 2016). "Since miRs are heavily implicated in various vascular diseases and given the importance of Kv7 channels in the vasculature, this study investigates whether miRs have a regulatory role on Kv7.4 and identifies that miR153 targets KCNQ4, which may contribute to vascular dysfunction in hypertension." (PMID 27389411, 2016).
sensorineural hearing loss (5 papers, 2012 to 2025). "Conversely, heterozygous variants of the KCNQ4 gene, transmitted in an autosomal dominant (AD) manner, can cause isolated sensorineural hearing loss (DFNA2A)." (PMID 40178561, 2025). "We sequenced KCNQ4 from Japanese patients with sensorineural hearing loss, and identified a novel missense mutation encoding a Tyr270His located at the N-terminus of the highly conserved pore helix sequence." (PMID 22420747, 2012). "This study aimed to determine the frequency and clinical characteristics of pathogenic, likely pathogenic, and uncertain variants in the KCNQ4 gene among patients with sensorineural hearing loss of unknown origin in North Spain." (PMID 40178561, 2025). "In addition, mutations in KCNQ4 and STRC can induce sensorineural deafness, but this has not been found with PAX6." (PMID 29922125, 2018).
breast carcinoma (4 papers, 2020 to 2025). "This study demonstrated that miR-658 or miR-4739 inhibited the expression of KCNQ4 protein in breast cancer cells, and the expression of miR-658 or miR-4739 was negatively correlated with the expression of KCNQ4 in human and nude mouse breast cancer tissues." (PMID 36859185, 2023). "To verify the relative expression of KCNQ4 in breast cancer, we initially examined the normal breast and breast cancer tissues using HE staining, and verified the expression level of KCNQ4 in breast cancer through IHC immunohistochemistry IHC experiment." (PMID 37903775, 2023). "These experimental results suggest that miR-658 or miR-4739 can promote cancer by reducing the expression of KCNQ4 in breast cancer." (PMID 36859185, 2023). "To investigate the effect of KCNQ4 on breast cancer cells proliferation, we conducted EdU and MTT assay." (PMID 37903775, 2023). "Our results revealed the low expression of KCNQ4 in breast cancer." (PMID 37903775, 2023). "From this finding, we further investigated whether KCNQ4 is the target gene of BC069792 in breast cancer, and whether BC069792 exerts its tumor suppressor effect by regulating KCNQ4." (PMID 36859185, 2023). "Moreover, the mRNA and protein expression of KCNQ4 in normal breast tissue was significantly higher than that in breast cancer tissue." (PMID 36859185, 2023). "The rescue experiments showed that when BC069792 was overexpressed and miR-658 or miR-4739 was transfected simultaneously, the proliferation, invasion and migration abilities of breast cancer cells were reversed, and the expression level of elevated KCNQ4 protein was decreased." (PMID 36859185, 2023). "In addition, we analyzed the survival time of patients with breast cancer, stratified by high or low KCNQ4 expression, using the PrognoScan database in GEO." (PMID 37903775, 2023). "The wound healing assay demonstrated that KCNQ4 could inhibit the migration of breast cancer cells MDA-MB-231 and MDA-MB-468." (PMID 37903775, 2023). "Moreover, overexpression of KCNQ4 inhibited the migration, proliferation and invasion, while promoting the apoptosis of breast cancer cells." (PMID 37903775, 2023). "Through IHC experiments and cultured cell experiments, it is proved that the decreased expression of KCNQ4 in breast cancer can inhibit proliferation, migration, invasion and promote apoptosis of tumor cells, indicating its potential as a target for cancer therapy." (PMID 37903775, 2023). "Expression of KCNQ4 in breast cancer tissue was lower than normal tissue." (PMID 37903775, 2023). "Furthermore, we used wound healing and transwell assay to evaluate the impact of KCNQ4 on the migration and invasion of breast cancer cells." (PMID 37903775, 2023). "We hypothesized that KCNQ4 as a anticancerous gene in breast cancer." (PMID 37903775, 2023). "The results showed that breast cancer cells overexpressed BC069792 with reduced proliferation ability, weakened migration ability, and increased KCNQ4 protein expression level." (PMID 36859185, 2023). "The EdU proliferation assay, the results revealed that breast cancer cells MDA-MB-231 and MDA-MB-468 with overexpressed KCNQ4 plasmid exhibited significantly reduced proliferation rates compared to the control group." (PMID 37903775, 2023). "The target miRNAs that can bind to BC069792 and KCNQ4 were predicted through miRWalk, RegRNA2.0 and other websites and ENCORI database, and the differentially expressed miRNAs in breast cancer and normal breast tissues were screened through the TCGA database." (PMID 36859185, 2023). "The MTT proliferation assay indicated that the proliferation rate of breast cancer MDA-MB-231 and MDA-MB-468 cells transfected with KCNQ4 plasmid was significantly lower than that of the control group." (PMID 37903775, 2023).
breast carcinoma (continued). "When BC069792 was simultaneously overexpressed with hsa-miR-658 or hsa-miR-4739, the inhibition of breast cancer cell proliferation and migration by BC069792 was reversed, the elevated KCNQ4 protein expression level was decreased, and the level of reduced p-AKT protein was increased." (PMID 36859185, 2023). "Mechanically, BC069792 acts as a molecular sponge to adsorb hsa-miR-658 and hsa-miR-4739, to up-regulate the protein expression of Potassium Voltage-Gated Channel Q4 (KCNQ4), inhibits the activities of JAK2 and p-AKT, and plays a role in inhibiting breast cancer growth." (PMID 36859185, 2023). "The results indicated that breast cancer patients with low expression of KCNQ4 had longer OS (P = 0.00459, HR = 0.88), DMFS (P = 0.041356, HR = 0.25), and RFS (P = 0.041356, HR = 0.25) compared to those with high expression of KCNQ4, suggesting a more favorable prognosis." (PMID 37903775, 2023).
hearing disorder (2 papers, 2021 to 2023). A disorder characterized by the partial or complete loss of the ability to detect sounds due to damage to the ear structures or inability of the brain to properly interpret or process the auditory signals it receives from the anatomic structures of the ear. "As commented in Results, 3 of these genes (Gata3, Kcnq4 and Kit) are associated to hearing disorders in both mouse and human." (PMID 36999169, 2023).
non-syndromic deafness (2 papers, 2015 to 2022). "KCNQ4 channels are expressed on hair cells and spiral ganglion neurons and the mutation of KCNQ4 accounts for human non-syndromic deafness DFNA2 an autosomal dominant hearing loss." (PMID 25904892, 2015).
prostate carcinoma (2 papers, 2022 to 2023). A carcinoma that arises from epithelial cells of the prostate gland. "Among the four CpGs passing a Bonferroni‐corrected threshold in MR analyses, cg06885782 in KCNQ4 was reported to be associated with risk for prostate cancer (beta = 1.2, pMR = 4.1 × 10−4) and negatively associated with longevity (beta = −1.9, pMR = 0.02)." (PMID 35546478, 2022). "For example, cg06885782 (in KCNQ4) was positively associated with risk for prostate cancer (Beta = 1.2, PMR = 4.1 × 10−4) and negatively associated with longevity (Beta = −1.9, PMR = 0.02)." (PMID 35546478, 2022).
aortic aneurysm (1 paper, 2021). A ruptured aneurysm located in the wall of the proximal portion of the descending aorta proceeding from the arch of the aorta. "In the present study, the PheWAS data implied an association of the KCNQ4 variant with aortic aneurysm and diabetic polyneuropathy." (PMID 34828318, 2021). "We found an association between KCNQ4 and aortic aneurysm (OR: 4.97, p = 6.3 × 10−4), fracture of lower limb (OR: 3.31, p = 7.1 × 10−4) and polyneuropathy in diabetes (OR: 7.67, p = 8.4 × 10−4)." (PMID 34828318, 2021). "Additionally, we found a significant association between KCNQ4 c.546C>G variant, aortic aneurysm, fracture of lower limb and polyneuropathy in diabetes." (PMID 34828318, 2021).
autism spectrum disorder (1 paper, 2019). A spectrum of developmental disorders that includes autism, and Asperger syndrome. "In HGMD Professional, 36 KCNQ4 variants have been reported, with most of them linked to ADNSHL except the c.1525 G > T;p.E509* variant, which is associated with autism spectrum disorder." (PMID 31434872, 2019).
autosomal dominant deafness type 2A (1 paper, 2014). "Twelve known missense mutations in the KCNQ4 transmembrane region lead to autosomal dominant deafness type 2A (DFNA2A) with late-onset progressive hearing loss." (PMID 24609033, 2014).
developmental delay (1 paper, 2019). "Nine pathogenic CNVs, including KCNQ4, are mostly linked to severe phenotypes, such as global developmental delay, intellectual disability, and cardiac defects." (PMID 31434872, 2019).
hearing (1 paper, 2021). "The novel in-frame deletion variant, p.A271_D272del is located in the pore-loop domain of KCNQ4, where the majority of known KCNQ4 variants are linked to the hearing loss cluster." (PMID 34316018, 2021).
irritable bowel syndrome (1 paper, 2014). Irritable bowel syndrome (IBS) is a chronic functional condition of the lower gastrointestinal (GI) tract characterized by abdominal pain or discomfort and disordered bowel habit (diarrhea, constipation, or fluctuation between the two). "Recent studies showed that the KCNQ4 and KCNQ5 genes encode components of the M channel expressed in gastrointestinal smooth muscles and suggested that these genes are associated with irritable bowel syndrome and similar peristalsis diseases." (PMID 25127363, 2014). "Recent studies showed that KCNQ4 and KCNQ5 genes encode members of the M channel expressed in gastrointestinal smooth muscle and suggested that these genes are associated with irritable bowel syndrome and similar peristalsis diseases." (PMID 25127363, 2014).
squamous carcinoma (1 paper, 2023). "Our analysis revealed that the low expression of KCNQ4 correlated with longer OS in BRCA, LUAD (adenocarcinoma), ESCA, and PCPG, while the high expression of KCNQ4 was associated with shorter OS in KIRP, LUSC (squamous carcinoma), HCC, and UCEC patients." (PMID 37903775, 2023).
tumor (5 papers, 2016 to 2023). "In our study, we discovered a positive correlation between KCNQ4 and tumor-associated fibroblasts in BLCA, BLCA-LumA, CESC, HNSC, HNSC-HPV-, KIRC, PRAD and STAD." (PMID 37903775, 2023). "In this study, we sought to investigate the potential association between the stemness index and immune cells by analyzing KCNQ4 in each tumor via DNAss and RNAss STEMNESS scores based on methylation signature." (PMID 37903775, 2023). "As the characteristics of different tumors are different, it also needs clinical verification, which also provides a new idea for tumor immunotherapy, and further establishes the value of KCNQ4 in the diagnosis and treatment of tumors." (PMID 37903775, 2023). "Although our comprehensive pan-cancer analysis provides insights into the tumor inhibitory effect of KCNQ4, there are still significant limitations that need to be addressed in the future KCNQ4 analysis of key tumors." (PMID 37903775, 2023). "The results showed a significant decrease in KCNQ4 expression in tumor tissue compared to normal tissue." (PMID 37903775, 2023). "Next, to investigate the relationship between KCNQ4 expression and tumor development, we analyzed the expression of KCNQ4 in patients with TCGA cancer types, based on their respective cancer stages." (PMID 37903775, 2023). "In summary, our comprehensive pan-cancer analysis highlights the potential of KCNQ4 as a cancer marker, and can be used as an auxiliary prognostic indicator and an indicator for immunotherapy in certain tumor types." (PMID 37903775, 2023). "We used multiple databases to determine the expression, prognosis and other characteristic of KCNQ4 shows that the expression of KCNQ4 is low expression in most tumor types." (PMID 37903775, 2023). "Similarly, the analysis based on MSI revealed a positive correlation between KCNQ4 and several tumor types, namely LGG, LUSC, READ, BLCA, and ACC." (PMID 37903775, 2023). "Our study results on the dryness of KCNQ4, TMB and MSI emphasize the strong correlation between the expression of KCNQ4 and the dryness and heterogeneity of tumor genomes, especially in BRCA, CESC, LIHC, BLCA, which may play a role in improving the status quo of clinical treatment of cancer." (PMID 37903775, 2023). "A Venn diagram depicted a positive correlation between KCNQ4 and tumor stemness in CESC and BRCA, while a negative correlation was observed in LIHC and BLCA." (PMID 37903775, 2023). "By IHC and vitro assays, we confirmed that KCNQ4 was low in BRCA and acted as a tumor suppressor." (PMID 37903775, 2023).